ESR1 (estrogen receptor 1)
Diseases named in the same sentence as ESR1 in open-access papers (continued):
Sharing a sentence is not in itself a finding about the gene and the disease.
tumor (continued). "Activating ESR1 mutations can contribute to tumor cell resistance through several mechanisms." (PMID 38791941, 2024). "Whether ESR1 mutations are enriched in low-grade gynecological malignancies could not be determined because of the restricted information regarding tumor histology subtypes." (PMID 38791941, 2024). "Detectable ESR1 mutations in circulating tumor DNA were detected in 47.8% of patients." (PMID 38869741, 2024). "Studies have shown that ESR1 mutations can promote tumor progression and metastasis." (PMID 37799727, 2023). "They include regulation of ESR1 expression by epigenetic factors, mutations of ESR1, alternative splicing events, alterations in the hormone-binding domain, differential recruitment of coregulators, factors of the tumor microenvironment and many others." (PMID 37065867, 2023). "Tracking ESR1 mutations through the use of circulating tumor DNA (ctDNA) may be a useful tool to identify tumor molecular dynamics, improving the personalization of treatments for mBC patients." (PMID 36831647, 2023). "Collectively, our data suggest that ESR1 pathway reactivation by gene mutation or amplification may account for tumor resistance and relapse in roughly 15% of HR+ HER- BC patients." (PMID 36595552, 2023). "Notably, we identified some subclones in the T2 tumor exhibiting an ESR1 p.R548H mutation that were missed in bulk sequencing." (PMID 37644058, 2023). "NGS can also be used as a cross-validation technique in cases of validation of the method, a great example being the cross-validation of droplet digital PCR (ddPCR) for the real-time detection of ESR1 mutation in the PADA-1 trial (PAlbociclib and Circulating Tumor DNA for ESR1 Mutation Detection)." (PMID 37958343, 2023). "ESR1 mutations express a unique transcriptional profile that favors tumor progression, suggesting that selected ESR1 mutations may influence metastasis." (PMID 36831644, 2023). "In recent years, circulating tumor DNA (ctDNA) has proven to be a more accurate, reliable, and convenient way to capture ESR1 mutations, making liquid biopsy a great option for regular testing using either Next Generation Sequencing (NGS) or digital droplet PCR (ddPCR)." (PMID 37958343, 2023). "Moreover, high ESR1 methylation was associated with tumor progression and predicted a poor prognosis." (PMID 37881785, 2023). "ESR1 mutations have emerged as a key mechanism of aromatase inhibitor (AI) resistance in HR + metastatic breast cancer and can be monitored using circulating tumor DNA (ctDNA)." (PMID 37924026, 2023). "Primary endpoints of centrally reviewed PFS in all patients (intent-to-treat (ITT) population, n = 477) and in patients with detectable ESR1 mutations from circulating tumor DNA (ctDNA) were met (hazard ratio (HR) 0.70, P = 0.002 and HR 0.55, P = 0.0005, respectively)." (PMID 37684290, 2023). "In early BC, mutations in the ER gene (ESR1) cannot be found in tumor tissue." (PMID 38001722, 2023). "A comparison of ESR1 variant detection in tissue and plasma in 171 advanced BCs by dPCR revealed 97% concordance with 75% sensitivity and 100% specificity for ctDNA analysis compared to tumor DNA." (PMID 38001722, 2023). "Interestingly, it is known that ESR1 mutations respond differently to treatment due to the polyclonal origin of such ESR1 variants, in addition to high tumor molecular heterogeneity." (PMID 36831647, 2023). "Comparison of the orally bioavailable investigational SERD elacestrant, versus fulvestrant, demonstrates both drugs impact tumour growth of ER+ patient-derived xenograft models harbouring several ESR1 mutations but that elacestrant is active after acquired resistance to fulvestrant." (PMID 36446866, 2022).
tumor (continued). "We detected an ESR1 mutation in a primary HR+ tumor and the corresponding CM." (PMID 35267459, 2022). "In some hormone‐receptors‐positive MBC, ESR1 mutation detection antedates tumor progression and may be a useful biomarker to adapt endocrine therapy." (PMID 35122700, 2022). "The level of evidence for the use of circulating tumor DNA monitoring, including ESR1 mutation, is improving, with prospective trials that have longitudinally evaluated the predictive and prognostic role of ctDNA in the metastastic setting, such as the PADA-1 trial or the BIOLTALEE trial." (PMID 36077738, 2022). "Methods for detection of circulating tumour cells (CTCs) and more readily, circulating tumour DNA (ctDNA) potentially allow for continual patient monitoring for emergence of ESR1 mutations and so, present opportunities for the early switchover of endocrine therapies once ESR1 mutations emerge." (PMID 36198774, 2022). "Six sex-specific, Esr1-dependent transcripts–A1bg, Fmo3, Cabyr, Cspg5, Mthfd1l, Tff3–are strongly implicated in hepatocarcinogenesis based on their expression, prognostic power, or oncogenic/tumor suppressive properties." (PMID 34068249, 2021). "Furthermore, a highly dynamic evolution of the tumor was observed: The ESR1 mutation E380Q was identified at T3 and T13." (PMID 34885114, 2021). "Although ESR1 mutations were more commonly identified in metastatic BCs, the use of the sensitive droplet-digital PCR reported higher frequencies in primary tumours." (PMID 34499316, 2021). "In cases of ESR1 mutation-positive metastatic disease, the matched primary tumors when tested have been predominantly mutation negative, suggesting that many of these mutations are selected for under therapeutic pressure and during tumor progression." (PMID 33937624, 2021). "An increasing number of studies support the association between ESR1 and tumor immune defense." (PMID 34784845, 2021). "Importantly, our model harbors a naturally occurring ESR1 mutation, and immune-humanization recapitulates the lymphocyte-excluded and myeloid-rich tumor microenvironment of human ER+ breast tumors." (PMID 34717714, 2021). "Thus, subclonality, polyclonality, and distinct effects of different ESR1 mutations demonstrate the utility inherent in liquid biopsy as compared to solid tissue sampling in characterizing the tumor ecosystem." (PMID 34392831, 2021). "Incidence of tumor heterogeneity within metastases may also occur more frequently relative to primary sites—including occurrence of ESR1 mutations in metastases that lead to acquired resistance to antiestrogen therapy (such as aromatase inhibitors)." (PMID 32697890, 2020). "Interestingly, we found that ESR1, encoding oestrogen receptor 1, was also highly methylated in primary tumour and LNM." (PMID 32971738, 2020). "ESR1 mutations have been identified in ET resistant BCa tumours." (PMID 32932819, 2020). "Plasma ctDNA analyses have shown therapeutic benefits and can help understand tumor evolution, including mechanisms of resistance such as acquired ESR1 mutations that induce aromatase inhibitor resistance in BAC and EGFR resistance to 1st and 2nd generation EGFR tyrosine kinase inhibitors in NSCLC." (PMID 32188081, 2020). "However, the relative endocrine resistance of the xenograft tumor models ectopically expressing ESR1 mutations was evident when the sizes of the different tumor models within the endocrine-treated group are compared, similar to our observations." (PMID 32771039, 2020). "In LIHC and UCEC, ESR1 expression was associated with proliferation and mitotic genes, and correlation analysis showed that ESR1 was negatively correlated with proliferation and cell cycle genes in most tumor types." (PMID 32536040, 2020).
tumor (continued). "The S282C ESR1 mutation was identified in a single BCa tumour." (PMID 32932819, 2020). "Hotspot mutations in the ER ligand-binding domain (LBD), such as the D538G and Y537S, can provide tumor cells a growth advantage, suggesting that these ESR1 mutations, to an extent, may display innate resistance to CDK4/6 inhibitors." (PMID 31852484, 2019). "Using the mRNA level of ESR1, which encoded the ERα protein, as the phenotypic label, 1019 tumor tissue samples were divided into the high-ESR1 group (N = 509) and the low-ESR1 group (N = 510), the median value of ESR1 expression level was used as cut-off criterion." (PMID 31511014, 2019). "Toy at al. demonstrated that LBD ESR1 mutations found in this hotspot region exhibit a constitutively ligand-independent ER activity, which activates ER transcription function, promoting hormone-independent tumor cell growth." (PMID 31795152, 2019). "ESR1 mutations appear to drive oestrogen-regulated processes in resistant tumours." (PMID 30563991, 2019). "PADA -1 (“Palbociclib and Circulating Tumor DNA for ESR1 Mutation Detection”) (NCT03079011) is an ongoing trial designed to evaluate the efficacy of a switch in ET (AI changed to fulvestrant) combined with palbociclib at the time that ESR1 mutations are detected in ctDNA on treatment." (PMID 31795152, 2019). "Validity of findings was assessed in another five ESR1-mutated tumours progressing on AI." (PMID 30563991, 2019). "Importantly, a case study showed that E2 therapy caused partial tumor regression in a patient with ESR1‐amplified metastatic breast cancer." (PMID 31180176, 2019). "Indeed, patients progressing on palbociclib exhibited a relative high frequency of PIK3CA and ESR1 mutations in plasma tumor ctDNA." (PMID 30914635, 2019). "The ESR1 mutations are infrequent in the primary tumor, but their frequency in metastatic lesion may be even 30-times higher." (PMID 30382472, 2019). "However, in the ESR1-mutated AI-resistant tumours, expression of four classical oestrogen-regulated genes (ERGs) was sevenfold higher than in ESR1 wild-type tumours, a finding confirmed in the second set of ESR1-mutated tumours." (PMID 30563991, 2019). "Furthermore, ESR1 mutations located in four hot-spots (Y537N/S/C, D538G) count for 74% of all described mutations, and can be successfully detected in circulating tumour DNA (ctDNA)." (PMID 29769099, 2018). "cfDNA sequencing identified an ESR1 mutation, potentially explaining a patient’s resistance to aromatase inhibition, and gave insight into how metastatic lesions differ from the primary tumor." (PMID 26317216, 2015). "Interestingly, tumour mRNA expression of ESR1 (71 cases, 24.8%) was strongly associated with inferior DFS (HR = 2.33, 95% CI 1.35–4.02, p<0.001) and OS (HR = 1.74, 95% CI 1.02–2.97, p = 0.04)." (PMID 25970543, 2015). "The somatic mutation profile of a tumour may contribute to this; for example, tumours harbouring or acquiring driver mutations in ESR1 or ERBB2 or amplifications at 8p12 (FGFR1) or 11q13 (CCND1) may be less responsive to targeted endocrine therapy." (PMID 25849106, 2015). "This may be a characteristic of ER−ve tumours or, alternatively, the measurement error associated with low levels of ESR1 transcript could preclude detection of a significant correlation in microarray data." (PMID 21552322, 2011). "A cluster enriched for genes associated with the luminal/ER+ tumor subtypes (N-acetyltransferase 1, estrogen receptor 1, putative G-protein-coupled receptor, trefoil factor 3, GATA binding protein 3, and X-box binding protein 1) was also present in this gene set." (PMID 17150101, 2006). "In addition, estrogen receptor 1 (ESR1) mutations may be important in unravelling differences in the efficacy of (extended) aromatase inhibition in patients with luminal A versus B tumours." (PMID 39921934, 2025).
tumor (continued). "The significant hydrogen bonding and hydrophobic contacts in ESR1’s ligand-binding domain indicate that medicarpin may operate as a partial antagonist, diminishing estrogen-mediated transcriptional activities linked to tumor growth." (PMID 41516052, 2025). "Furthermore, its association with ESR1 indicates possible compatibility with hormonal treatments or immune checkpoint inhibitors that may benefit from increased tumor immunogenicity resulting from apoptotic priming." (PMID 41516052, 2025). "Significant progress has been made with the discovery of ESR1 mutations, which are detectable in less than 1% of primary BC, but are enriched in metastatic luminal BC during adjuvant ET (in up to 15%–30%) and lead to ligand-independent autocrine tumor cell growth." (PMID 40705465, 2025). "Importantly, we discovered pan-cancer PM-associated mutation of ESR1 previously linked to metastasis, suggesting conserved molecular determinants across tumor types that could enable early detection and targeted therapies." (PMID 41390696, 2025). "For HR+ HER2- BC seeking a second-line option, a targeted NGS BC panel is very useful to tell whether the tumor harbors an actionable mutation in critical BC-related genes, including ESR1, PIK3CA, AKT1, PTEN, as well as additional genes in the PI3K pathway or other synergetic pathways." (PMID 39796647, 2024). "A composite biomarker signature incorporating low Rb score (defined as <1% tumor cells with positive nuclear staining on immunohistochemistry), high cyclin E1 (defined as ≥10% tumor cells with positive nuclear staining on immunohistochemistry), and ESR1 mutation was associated with poorer PFS." (PMID 37035239, 2023). "Several research groups have used sensitive detection methods using patient liquid biopsies to track ESR1 or truncal somatic mutations to predict treatment outcomes and tumor progression, and these techniques may be used to guide patient treatment in the future." (PMID 36831644, 2023). "ESR1 mutations leading to constitutive activation of Estrogen Receptor alpha (ERα) were selected by pharmacological treatments leading to reduction of estrogen levels in peripheral blood and in tumor microenvironment, such as LHRH analogues (LHRHa) and aromatase inhibitors (AIs)." (PMID 36595552, 2023). "Along this line, we reported a case harboring an ESR1 mutation, in which the variant allele frequency raised from 2,6% in the primary tumor sample to 8,8% in the metastatic sample, letting us speculate that this could represent an example of clonal expansion upon therapy selective pressure." (PMID 36595552, 2023). "Therefore, monitoring ESR1 gene mutation in ABC progressing on AIs using liquid biopsy showed that ESR1 mutations were detected before the occurrence of any clinical or radiological tumor progression in up to 75% of cases." (PMID 37958343, 2023). "ESR1 is involved in the coordination of migration, angiogenesis, cancer stem-like properties, mobility, proliferation, and invasion of LC cells, and its genetic and expression status correlate with cancer susceptibility, tumor growth, metastasis, and prognosis of LC." (PMID 36118098, 2022). "Therefore, characterization only at the time of progression to hormone therapy may be inadequate because ESR1-mutated tumor cells may be the result of a clonal expansion of endometrioid cancer cells primarily refractory to hormonal treatment." (PMID 35359373, 2022). "However, tumours bearing ESR1 mutations can retain relative sensitivity to SERDs." (PMID 34638457, 2021). "ESR1 mutations that mutate its ligand binding domain constitute one of the most important driving mechanisms of endocrine resistance, whereas the growth of the xenograft tumor models ectopically expressing ESR1 mutations can be effectively inhibited by endocrine treatment." (PMID 32771039, 2020).
tumor (continued). "Additionally, the development of targeted therapies directed to tumor cells harboring ESR1 mutations is a logical and appealing concept, and extensive preclinical research has been conducted in this field, and promising work evaluating treatment with new generation endocrine agents is in progress." (PMID 32309212, 2020). "Notably, only one of our tumor samples demonstrated a mutation of ESR1 (estrogen receptor 1)." (PMID 32881420, 2020). "Of note, within individual patients, HER2 and ESR1 subclonal mutations appeared at different allele frequencies, raising the possibility that these two distinct resistance mechanisms contribute toward the full complement of drug resistance in heterogeneous tumor populations." (PMID 31341951, 2019). "Therefore, our data on ESR1 mutation presented here was independent on tumor burdens." (PMID 27102299, 2016). "Intriguingly, the selective GR modulators (SGRMs) C134 and C335 were shown to reduce MCF-7 ESR1 mutant primary tumor growth by decreasing the expression of CCND1." (PMID 41261233, 2026). "They assessed ctDNA at treatment initiation and completion using a targeted amplicon panel for tumor purity evaluation and ddPCR for PIK3CA/ESR1 mutation detection." (PMID 40050490, 2025). "Given this tumor-suppressive role, ESR1 was excluded from further analysis focused on drug inhibition effects." (PMID 41048345, 2025). "scRNA-seq revealed compartment-specific target localization: AKT1/ESR1 in tumor cells, SRC/IL6 in myeloid cells, and MTOR/HIF1A across stromal compartments." (PMID 40746726, 2025). "The EMERALD trial demonstrated that elacestrant, the first approved oral SERD, significantly improved progression-free survival (PFS) in patients with ESR1-mutant tumours who had received two prior lines of AI-based endocrine therapy." (PMID 41364261, 2025). "MiR-4728-5p triggers a positive feedback loop to promote HER2-dependent tumor progression, while the isoform miR-4728-3p downregulated estrogen receptor 1 (ESR1) expression." (PMID 40244378, 2025). "The positive correlations of miR-30a and MLL with ESR1 indicate their key roles in chromatin remodeling and in the activation of tumor suppression." (PMID 40243758, 2025). "In this study, we found that markedly increased IF1 expression patterns in HCC contribute to tumor growth and VM formation via the ESR1 and miR-20a-3p/GNAZ/ERK pathway." (PMID 41306771, 2025). "(L) Statistical analysis of Frmd8, Esr1 and Pgr expression in normal and tumor cells from MMTV-Cre-; Frmd8fl/fl; PyMT and MMTV-Cre+; Frmd8fl/fl; PyMT mice." (PMID 40213945, 2025). "Endocrine therapy is known to promote clonal expansion of ESR1 mutant tumor cells, leading to endocrine resistance." (PMID 39839709, 2025). "Cases harboring detectable ESR1 mutations at week 12 were significantly associated with poor PFS, suggesting that the poor response to palbociclib results in sustained detection of tumor-associated variants in cfDNA." (PMID 41123599, 2025). "Further investigation of gene expression across different tumor stages using GEPIA showed that ESR1 expression was significantly elevated in stages II, III, and IV (P = 0.0268)." (PMID 40259338, 2025). "CYP4B1, CYP4F12, and CYP4F3 gene expression levels were found to correlate with ESR1; then, a tumor versus normal tissue analysis and an overall survival evaluation in several types of cancer were conducted." (PMID 40723371, 2025).